TLR7 (toll like receptor 7)
Diseases named in the same sentence as TLR7 in open-access papers (continued):
Sharing a sentence is not in itself a finding about the gene and the disease.
tumor (continued). "Although we observed delayed tumor growth, administration of TLR7/8 agonists did not significantly increase the percentage of NK cells for any of the chemicals, which were similar to those of tumor-bearing mice without treatment." (PMID 41597427, 2026). "Further genetic ablation experiments demonstrated that c-Jun in cDCs functioned downstream of TLR7 signaling to mediate the antitumor effect of IL-12 while simultaneously inducing the secretion of CCL2, which recruited pDCs to the TME for direct tumor suppression." (PMID 40547481, 2025). "Although survival analyses of TLR7 and TLR8 expression are confounded by their expression both in tumour cells and in immune cells, the strict tumour specificity of HERVH Xp22.2-AS expression reflects tumour cell-intrinsic transcriptional states." (PMID 40336011, 2025). "As an agonist of TLR7 and TLR8, resiquimod (R848)-loaded β-cyclodextrin nanoparticles (CDNP-R848) induced a repolarization of M2-like TAMs shifted toward a M1-like TAM phenotype, leading to the reduction of tumor growth in multiple murine tumor models." (PMID 40050933, 2025). "The mechanism involves c-Jun/AP-1 mediating TLR7/8 signaling in IFN-I-primed DCs, upregulating the pDC-recruiting chemokine CCL2 and the anti-angiogenic cytokine interleukin-12, which suppresses VEGF-A production leading to tumor necrosis and regression." (PMID 39849091, 2025). "Moreover, Wang Ruonan’s team designed a DC-targeting nanoregulator (DNR) that reprograms dendritic cells in tumor-draining lymph nodes (TDLNs) by synergistically activating TLR4 (via mannan) and TLR7/8 (via an IMDQ prodrug) signaling pathways." (PMID 41488647, 2025). "In addition, researchers found that compound 558, as a single drug, can regulate TLR7/8 and STING, activate inflammasome pathways, and significantly reduce the growth rate of tumor in vivo." (PMID 41516215, 2025). "This further verified that the synergy between oral and local IMQ was based on oral-IMQ-induced IFN-I production by pDCs, which in turn led to the upregulation of TLR7 on cDCs in the TME, thereby sensitizing these immune cells to local IMQ treatment at the tumor site." (PMID 40547481, 2025). "TLR7 and TLR8 agonists reverse TAMs from M2 to M1, reducing radiation resistance and tumor growth." (PMID 40948759, 2025). "TLR7 (Toll-like receptor 7) and STING (Stimulator of Interferon Genes) are important components of innate immune responses, playing crucial roles in the defense against pathogen infection, anti-tumor immune responses, and cellular autophagy." (PMID 41516215, 2025). "Furthermore, in a preclinical study, an antagonist of TLR9 and TLR7 labeled as HJ901 was investigated and was observed to inhibit tumor cell proliferation in animals and on three of five ABC but not GCB cell lines." (PMID 40437466, 2025). "Notably, a sex-dependent response emerged in mice vaccinated with MUC1 C3-liposomes with TLR agonists (TLR4, TLR7/8, and TLR9); male mice exhibited greater tumor suppression than females." (PMID 40284463, 2025). "Whereas their ligation in immune cells may enhance anti-tumour activity, TLR7 and TLR8 are also expressed in tumour cells where they mediate a pro-tumour effect." (PMID 40336011, 2025). "Apoptotic cells emit single-stranded RNA, which stimulates Toll-like receptor 7 (TLR7) in adjacent tumor cells, initiating a non-canonical gene expression program that facilitates metastasis." (PMID 40092993, 2025). "NPs loaded with vR848 (an agonist of the toll-like receptors TLR7 and TLR8) were delivered to tumor tissues in an immunocompetent mouse model of colorectal cancer (MC38) in C57BL/6 mice and promoted the M1 phenotype of TAMs as well as suppressed carcinogenesis." (PMID 39516356, 2024). "Not surprisingly, immunofluorescent staining of the same tumor tissues with antibodies to FRβ and TLR7 confirmed that FRβ and TLR7 colocalize only in tumor macrophages." (PMID 38384467, 2024).
tumor (continued). "In vertebrates, the interaction between HMGB3 and TLR3, TLR7, and TLR9, which occurs on the membrane, leads to upregulation of the production of ROS and activation of NF-kB signaling, which ultimately regulates tumor growth and metastasis." (PMID 39062899, 2024). "Moreover, TLR agonists like Diprovocim (TLR1/2), 1V270 (TLR7) and SD-101 (TLR9) have shown synergistic effects with immune checkpoint inhibitors thus enhancing the tumor immunogenicity." (PMID 39318624, 2024). "Analysis of treated tumors demonstrates that targeting of a Toll-like receptor 7 agonist inhibits Treg expression of FOXP3, PD-1, CTLA4, and HELIOS, resulting in 40-80% reduction in tumor growth and repolarization of other tumor-infiltrating immune cells to more inflammatory phenotypes." (PMID 37928524, 2023). "Our results thus support the notion that globally, TLR7 has no exclusive tumor‐promoting or tumor‐suppressive functions in PDAC." (PMID 36602302, 2023). "With this fortuitous distinction, it became possible to deliver a potent TLR7 agonist to tumor resident Tregs without altering their properties elsewhere, leading to a ~40-80% reduction in tumor growth without inducing obvious systemic toxicities." (PMID 37928524, 2023). "There is a growing body of preclinical evidence that agonists targeting TLR3, TLR5, TLR7/8, or TLR9 in combination with RT may lead to enhanced anti-tumor immunity." (PMID 37112730, 2023). "Moreover, the combined administration of TLR7 and TLR9 agonists with PD-1 blockade in HNSCCs suppresses tumour growth and progression related to TAMs and CD8+ T cell activation and increases the ability of DCs to gain a mature phenotype and migration." (PMID 36980527, 2023). "In pancreatic ductal adenocarcinoma (PDAC), R848 was shown to primarily act on stromal cell TLR7 rather than tumor cells and induce CD8 T-cell infiltration, activation and cytotoxicity, and decrease Treg cells." (PMID 37112730, 2023). "However, when they are re-modulated by TLR7/TLR9 ligands, their tolerogenic phenotype gets shifted to activated form and mediate effective anti-tumor immunity through the activation of myeloid DCs, NK cells, and CD8+ T cells in solid tumors." (PMID 37122749, 2023). "When activated, TLR7 and TLR9 on pDCs can secrete large amounts of IFN-I, which can both inhibit the proliferation of tumor cells and activate the immune system to exert anti-tumor effects." (PMID 37876967, 2023). "Liu and others modulated immunosuppressive tumor microenvironment (ITM) and overcome radioactivity by coupling the Toll-like receptor agonist TLR7/8a with a radiation-sensitive hydrogel (Smac-TLR7/8 hydrogel) to adjust TAMs repolarization from M2 type into M1 type." (PMID 36815890, 2023). "The addition of Resiquimod (R848), a TLR7/8 agonist, prevented tumor recurrence in 60% of mice while adjuvant DMXAA did not enhance long-term survival compared to CA alone, both resulting in an overall survival of 40%." (PMID 37190138, 2023). "Moreover, TLR7 ligation can affect the expression of p21 and p-STAT3 to regulate tumor stromal inflammation." (PMID 37803031, 2023). "Our own results surprisingly demonstrated neither a protective nor a tumor‐promoting net effect of TLR7 ablation in vivo, although tumor‐promoting functions in vitro were readily apparent." (PMID 36602302, 2023). "However, despite the anti-tumor efficacy of TLR 7/8a, the clinical applicability of TLR7/8a in cancer immunotherapy is currently limited to skin cancers, including metastatic cancers that present on the skin, due to severe systemic toxicity upon distribution." (PMID 37766179, 2023). "Intraperitoneal injection of the TLR7 agonist resiquimod in mice with pancreatic ductal adenocarcinoma (PDAC) tumors reduces Tregs in the TME, enhances activation, infiltration, and cytotoxicity of CD8+ T cells, suppressing tumor growth and improving survival." (PMID 37936697, 2023).
tumor (continued). "Furthermore, combining CPIs with application of intratumoral TLR7/8 activation results in myeloid cell activation and antigen-presenting cell (APC) maturation in the tumor microenvironment to augment the activity and specificity of adaptive immune responses." (PMID 36319717, 2023). "Another study with tumor biopsies from 154 stage I-III PDAC patients with tissue microarray slides and immunohistochemistry to assess expression of different TLRs showed strong TLR7 expression only in 14 (9%) patients." (PMID 36476317, 2022). "We treated CT26 tumor bearing mice with a single IT dose of TransCon TLR7/8 Agonist either with or without systemic anti-PD1." (PMID 36123697, 2022). "Additionally, clinical studies using local delivery of TLR7, TLR7/8, and TLR9 agonists have demonstrated encouraging early evidence of clinical anti-tumor efficacy." (PMID 36123697, 2022). "However, it is intriguing to note that intracellular expression of c-MYC, a recognised proto-oncogene located downstream of TLR7 and TLR9, can modify tumour cell sensitivity to Irofulven." (PMID 35801728, 2022). "GC vaccines, which were synthesized by covalent attachment of TLR7 agonist with MG7-Ag tetra-epitope, combined with 5- fluorouracil chemotherapy decreased tumor sizes and increased long-term survival rates by improving T cell responses and decreasing myeloid-derived suppressor cells (MDSCs)." (PMID 35311157, 2022). "Moreover, the combination of cetuximab with small synthetic compounds able to trigger both TLR7 and TLR8 in a dose dependent manner induced tumor growth inhibition and increased NK cell-mediated ADCC in a lung murine model." (PMID 36672572, 2022). "In a bilateral tumor setting, combination of TransCon TLR7/8 Agonist with systemic IL-2 potentiated tumor growth inhibition in both injected and non-injected tumors and conferred protection against tumor rechallenge following complete regressions." (PMID 36123697, 2022). "The polymer provided no tumor protection, verifying that the antitumorefficacy of the polymer is TLR7 agonist-dependent." (PMID 36313164, 2022). "To assess whether APCs showed evidence of activation in the TME following TransCon TLR7/8 Agonist treatment, we evaluated activation marker expression on APC subsets from tumor samples at various times post-treatment." (PMID 36123697, 2022). "TransCon TLR7/8 Agonist monotherapy promoted activation of antigen-presenting cells in the TME and tumor-draining lymph nodes, with evidence of activation and expansion of CD8+ T cells in the tumor-draining lymph node and TME." (PMID 36123697, 2022). "Moreover, BCG combined with R837 can increase BCG potential tremendously by up-regulating TLR7/4 and down-regulating the P70S6K1 protein, which are able to reduce the incidence of bladder cancer powerfully by controlling tumor proliferation and apoptosis." (PMID 35745800, 2022). "R848, which normally activates both TLR7 and TLR8 on DCs, macrophages and neutrophils, activates the CD56brightCD16− NK cell subpopulation only via TLR8, highlighting the potential role of TLR8-targeted infiltrating TME-NK cells as a novel tumor immunotherapy." (PMID 36365103, 2022). "Treatment with the TLR7 agonist imiquimod promotes the infiltration of CD4+ and CD8+ T cells, decreases the absolute number of Tregs in the tumor microenvironment and establishes anti-tumor immune memory in mice." (PMID 35680568, 2022). "Upon peritumoral administration, they observed lower tumor burden in the B16 tumor model at levels similar to that of free TLR7/8 agonist but without the systemic side effects." (PMID 34058283, 2021). "In animal models, the combination of IRE with a checkpoint inhibition and TLR7 agonist, not only improved the local effects of IRE but also generated therapeutic abscopal effects against small secondary tumours, modelling the potential eradication of distant micrometastatic disease." (PMID 34199031, 2021).
tumor (continued). "Moreover, this antiapoptosis effect TLR7 activation can be directed via infiltrated cytotoxic lymphocytes (CTL), NK, and DCs in the tumor microenvironment." (PMID 34124272, 2021). "Crosstalk between tumor cells and γδ T cells via TLR2 and TLR7 signaling has been reported." (PMID 34124272, 2021). "Tumour‐secreted miR‐21 and miR‐29 also act as paracrine agonists of TLRs, which through interacting with either murine TLR7 or human TLR8 on immune cells transmit signals between tumour cells and the microenvironment, leading to regulation of tumour metastasis." (PMID 33336901, 2021). "SLC15A4 is required for Toll-like receptor 7 (TLR7)- and TLR9-mediated type I interferon (IFN-I) production in plasmacytoid dendritic cells (pDCs) by the mTOR pathway, highlighting its role in regulating the immune response in the tumor microenvironment." (PMID 34168674, 2021). "TLR5, TLR7 and TLR9 are the best examples of TLRs that could reinforce the anti‐tumour activity of DCs." (PMID 33336901, 2021). "We performed a comprehensive analysis of tumor-infiltrating immune cells in a cohort of intrahepatic and extrahepatic BTC, including innate immunity members such as TLR7, TLR9, and adaptive immunity factors such as CD4 and CD8 as well as PD-1 and PD-L1 expression at protein level." (PMID 34573939, 2021). "Another TLR7/8 agonist, MEDI9197, was shown to activate pDCs and macrophages leading to interferon-α (IFN-α), IL-12 and IFN-γ release and subsequent antitumor T cell response and tumor regression in syngeneic murine models." (PMID 33572196, 2021). "However, TLR4, TLR7, TLR8, and TLR9 mediated chronic inflammations were found to have pro-tumor effects." (PMID 32746880, 2020). "The two dual TLR7/8 agonists, resiquimod and telratolimod (also known as MEDI9197 and 3M-052), have been observed to delay tumour growth when administered intratumourally in models of squamous cell carcinoma, melanoma, colon adenocarcinoma, breast cancer, and glioma." (PMID 33352882, 2020). "In particular, the activation of pDCs via TLR7/9 stimulation induces the expression of TNF-related apoptosis-inducing ligand (TRAIL), which mediates the cell death of TRAIL-sensitive infected cells and tumor cells, expressing either TRAIL-R1 or TRAIL-R2." (PMID 32054102, 2020). "Despite the substantially increased pDC numbers in peripheral blood of HIS-NOG-EXL mice, we detected TLR7/8 agonist responsive and thus functional pDCs only in certain tumor models independent of the mouse strain employed." (PMID 33013879, 2020). "Toll-like receptor 7 (TLR7) was mainly expressed in macrophages, plasmacytoid dendritic, NK, and B cells, but not in tumor cells." (PMID 33381518, 2020). "To confirm that cytokine secretion was immune cell dependent, we stimulated OVCAR-5 tumor cells in vitro with TLR7/8 and were not able to detect tumor cell line-derived IFN-α2 (data not shown)." (PMID 33013879, 2020). "Thirdly, TNM staging was lost in a large number of samples, so we failed to combine TIIC in OS, MSR1, and TLR7 with tumor stage and grade, which required further verification." (PMID 33381518, 2020). "By using the human pDC cell line GEN2.2, it has been demonstrated that TLR7 and TLR9 stimulation can induce a TRAIL-mediated cytotoxic activity in pDCs that could participate to the tumor cell clearance." (PMID 32054102, 2020). "DAC treatment increased the expression level of various tumor antigens in cells, the conjugated SZU-106 activated the TLR7 signaling both in DC cells to promote antigen-presenting, and in cytotoxic T cells to promote the secretion of pro-inflammatory cytokines." (PMID 32922200, 2020). "It therefore remains possible that with TLR7/8 agonists, lower doses or shorter courses of other therapies can be used to attain effective tumor response without exacerbating cachexia." (PMID 31615993, 2019).
tumor (continued). "In our whole population-based study, we retrieved 150 Finnish NPC cases and studied their tumour samples for TLR1, TLR2, TLR4, TLR5, TLR7, and TLR9 expressions by immunohistochemistry, and for the presence of EBV and high-risk HPVs with EBV RNA and HPV E6/E7 mRNA in situ hybridizations." (PMID 31238894, 2019). "In the murine studies that have shown negative effects of IFA on CD8 T cell responses to short peptides, an alternative vaccination approach using a water-soluble adjuvant preparation, including TLR7 agonist imiquimod and CD40 antibody induced more durable immune responses and better tumor control." (PMID 31248461, 2019). "However, our data revealed suppression of TLR5, TLR7, TLR8 and TLR10 in PBMCs from CRC patients, suggesting a possible flip in the expression of those receptors between the tumor and periphery which warrants further investigation." (PMID 31835892, 2019). "In multivariable-adjusted Cox regression analysis, the patients with positive TLR7 tumour expression had better overall survival than those with no TLR7 expression." (PMID 31238894, 2019). "Recently, systemic or intratumoral administration of TLR7 agonists, such as resiquimod and its related conjugate, has shown to induce efficient tumor regression by inhibiting TAM- or MDSC-mediated immune suppression in murine tumor models." (PMID 29568358, 2018). "A subsequent activation of TLR7 and TLR8 was seen when tumor-derived exosomes (miR-21 and miR-29a) were transferred to immune cells that resulted in activation of a pro-metastatic inflammatory response leading to tumor growth and metastasis." (PMID 30574163, 2018). "The small ligands IMMS activate both TLR7 and TLR8 similarly to the natural pathogens to yield a cascade of biochemical events that initially stimulate several type of cells, such as monocytes and NK/NKT, T, B, mast and tumor cells." (PMID 28582454, 2017). "The target tumor cells were added to BMDMs activated by the following TLR agonists; TLR1/2 agonist Pam3, TLR2/6 agonist LTA, TLR3 agonist poly(I:C), TLR5 agonist flagellin, TLR7 agonist CL264, and TLR9 agonist CpG." (PMID 29123526, 2017). "This suggests that the addition of an immunostimulatory TLR7 agonist is able to extend the repertoire of tumor-specific T cells to non-foreign antigens." (PMID 27890931, 2017). "Our results indicate that the markedly high tumor burden in Smad3 mutant mice results from aberrant Toll-like receptor (TLR) expression as well as Wnt signaling, and demonstrate functional regulation of TLR7 through Smad3." (PMID 27456065, 2016). "Our results confirm that the expression levels of TLR7, TLR9 and constituents of TGF-β signaling, OAZ1 and P-Para were significantly altered in the tumor tissues of Smad3+/− VD-deprived mice compared to the tumor tissues of wild type VD deprived mice tumor tissues." (PMID 27456065, 2016). "The therapy-induced increase of tumor-specific T cells was also demonstrated in ELISPOT assays, which was consistent with data from other groups reporting increased specific immune responses to antitumor vaccination when combined with a TLR7/8 agonist." (PMID 25609199, 2015). "As the major effect of the activation of TLR7 is the induction of IFN-γ, we observed that when EL4 tumour cells were co-cultured with lymphocytes from the surviving mice treated by SZU-101, especially with the lymphocytes from the CoAd i.t. group, IFN-γ release was significantly increased." (PMID 25887995, 2015). "Importantly, in EC xenografted mice, immunization with T7-OCT4 conjugate decreased the growth of the tumor dramatically up to 90 %, as compared to mice immunized with OCT4 protein or TLR7 agonist alone." (PMID 25990580, 2015). "Similarly, tumour-secreted miR-21 and miR-29a trigger prometastatic and inflammatory responses in macrophages through human TLR-8 or mouse TLR-7 signalling." (PMID 25203514, 2014).